HMGB1 (high mobility group box 1)
Diseases named in the same sentence as HMGB1 in open-access papers (continued):
Sharing a sentence is not in itself a finding about the gene and the disease.
breast carcinoma (continued). "In breast cancer, autophagy induced high-mobility group box 1 (HMGB1) secretion from CAFs further mediates CAF-CSC interaction and promotes tumorigenesis and therapeutic resistance in a Toll-like receptor 4 (TLR4)-dependent pattern." (PMID 35488263, 2022). "Although HMGB1 is a high potential target for early detection or treatment of cancers, its dual function in breast cancer remains to be elucidated in more detail." (PMID 35637945, 2022). "This review summarizes the functions and mechanisms of HMGB1 on regulating breast cancer, including autophagy, immunogenic cell death, and interaction with the tumor microenvironment." (PMID 35637945, 2022). "Nevertheless, several experiments have shown a positive correlation between HMGB1 and radiotherapy resistance in breast cancer." (PMID 35637945, 2022). "For example, IL-1β promotes the proliferation, migration, angiogenesis, and release of HMGB1 in smooth muscle cells, while IL-18 promotes the migration of breast cancer cells by down-regulating claudin-12 and inducing the P38/MAPK pathway." (PMID 36233009, 2022). "The direct effect of HMGB1 on breast cancer cell proliferation is accomplished predominantly through the interaction with retinoblastoma (RB) protein." (PMID 35637945, 2022). "Breast cancer cell-derived exosomes were also reported to induce autophagy of breast cancer cells by transferring miR-1910-3p while gastric cancer cell-derived exosomes were found to induce the autophagy of neutrophils via HMGB1/TLR4/NF-κB signaling." (PMID 36428401, 2022). "Although the overexpression of HMGB1 in breast cancer has been increasingly reported, the role of HMGB1 in breast cancer is still controversial due to its conflicting tumor-promoting and tumor-suppressive roles." (PMID 35610613, 2022). "Numerous studies have revealed the clinical value of HMGB1 in the diagnosis and therapy of breast cancer." (PMID 35637945, 2022). "There are a variety of miRNAs that can enhance the chemosensitivity of breast cancer cells by targeting HMGB1-mediated autophagy." (PMID 35637945, 2022). "High mobility group box 1 (HMGB1), an important factor in cancer occurrence and development was up-regulated in breast cancer tissues." (PMID 36226050, 2022). "Another circRNA, Hsa_circ_0003645 have also been proved that can regulate miR-139-3p/HMGB1 axis to promote breast cancer progression." (PMID 35637945, 2022). "Currently, a bidirectional interaction of HMGB1 between breast cancer cells and CAFs has been partially reported." (PMID 35637945, 2022). "A convincing body of evidence shows both increased expression of HMGB1 in several solid tumors and its critical role as an emerging prognostic factor in prostate cancer, breast cancer, and gastric cancer." (PMID 35727208, 2022). "In this present study, recombinant HMGB1-activated MDA-MB-231 breast cancer cell migration and invasion were investigated." (PMID 35610613, 2022). "Mechanistically, HMGB1 can promote angiogenesis and migration of breast cancer through the PI3K/AKT/HIF-1α pathway." (PMID 35637945, 2022). "Taken together, the findings in breast cancer in this study also added to the evidence that HMGB1-RAGE interactions in cancer progression are mainly transduced through PI3K/AKT, MAPKs, and NF-κB signaling pathways." (PMID 35610613, 2022). "There are several molecules functioning as key regulators of HMGB1-medaited autophagy in breast cancer." (PMID 35637945, 2022). "The extracellular effect of HMGB1 on cancer cells in 2-D culture of the breast cancer cell model showed enhanced cancer cell migration and invasion." (PMID 35610613, 2022). "In breast cancer, the synergy of berberine with theophylline induces HMGB1/Bcl-2-mediated apoptosis." (PMID 35637945, 2022). "These miRNAs targeting HMGB1 are commonly involved in the regulation of proliferation, migration and therapeutic resistance of breast cancer cells." (PMID 35637945, 2022).
breast carcinoma (continued). "Previous studies have identified several microRNAs that can target HMGB1 to inhibit autophagy in breast cancer cells, such as miR-129-5p, miR-142-3p, miR-107." (PMID 35637945, 2022). "Excessive release of high-mobility group box 1 (HMGB1) by autophagic CAFs was found to enhance stemness of luminal breast cancer cells and resistance to doxorubicin." (PMID 34769066, 2021). "This formula increased the paclitaxel chemosensitivity of breast cancer cells via the chemokine (C-X-C motif) ligand 1/HMGB1 autophagy axis." (PMID 34638242, 2021). "In contrast, another study showed that miR-129-5p enhances the sensitivity of breast cancer cells to paclitaxel by inhibiting autophagy and HMGB1, thereby increasing apoptosis." (PMID 34638242, 2021). "HN1L knockdown significantly inhibited the migration ability of breast cancer cell, which was recovered by HMGB1 over‐expression." (PMID 33191617, 2021). "Stemness of luminal breast cancer cells was enhanced depending on TLR4 stimulated by high-mobility group box 1 (HMGB1) from autophagic CAFs indicating high LC3II/TLR4 to be poor prognosis markers for breast cancer." (PMID 33990205, 2021). "Mechanistically, HN1L interacted with HSPA9 and affected the expression of HMGB1, playing a key role in promoting the invasion and metastasis of breast cancer cell." (PMID 33191617, 2021). "We thus demonstrated that the MEK/ERK signaling pathway is required for the HMGB1-induced TAM resistance of ERα+ breast cancer cells." (PMID 34182538, 2021). "The dynamics of HMGB1 in serum during NAC correlate with the treatment response in patients with advanced breast cancer, suggesting that the serum HMGB1 level is a circulating biomarker of ICD and treatment response." (PMID 34638242, 2021). "The results showed that the combination of nuclear HMGB1 and positivity for LC3B(+) puncta was an independent prognostic marker significantly associated with metastasis-free survival and improved breast cancer-specific survival." (PMID 33840390, 2021). "To further investigate the differential roles of TLRs 2 and 4 in the observed effects of HMGB1, we studied human colorectal cancer cells (Colo 205), human breast cancer cells (MCF-7) and human embryonic kidney cells (HEK293)." (PMID 34234778, 2021). "Overexpression of HMGB1 has been found in numerous human cancers, such as pancreatic cancer, prostate cancer, breast cancer, melanoma, colorectal cancer and leukemia." (PMID 33407071, 2021). "Here, we observed that AML patients had significantly higher levels of HMGB1 in their blood plasma compared to healthy donors and primary breast cancer patients." (PMID 34234778, 2021). "HMGB1 released by breast cancer cells is N-glycosylated at Asn37, which promotes the transition from monocytes to MDSC-like cells and contributes to M-MDSC differentiation from bone marrow through the p38/NFκB/Erk1/2 signaling pathway." (PMID 34283088, 2021). "Intracellular HMGB1 expression has been detected in fibroblasts conditioned medium (CM) treated breast cancer cells and in doxorubicin-treated cells." (PMID 34283088, 2021). "For instance, miR-107 has been proven to inhibit breast cancer cells proliferation, migration and autophagy in vivo and in vitro by targeting HMGB1." (PMID 33761957, 2021). "The present study clearly illustrated that radiotherapy-triggered HMGB1 contributed to M1-macrophage-facilitated systemic anti-tumor abscopal response in breast cancer." (PMID 33867819, 2021). "It was also discovered that miR-107 and miR-1179, whose expression was downregulated in breast cancer and gastric cancer, respectively, inhibited autophagy, proliferation, and/or migration of tumor cells by directly suppressing HMGB1." (PMID 34073766, 2021). "In our rescue experiment, over‐expression of HMGB1 in HN1L‐silenced breast cancer cells saved the migration ability of breast cancer cells, which suggests that HNIL affects the migration ability of breast cancer cells by regulating the expression of HMGB1." (PMID 33191617, 2021).
breast carcinoma (continued). "The antitumor role of the miR-129-5p/HMGB1 axis was studied in osteosarcoma, hepatocellular carcinoma, breast cancer, gastric cancer, and colon cancer." (PMID 34073766, 2021). "Serum HMGB1 has also been shown to decrease following treatment in breast cancer, and was demonstrated to correlate with treatment efficacy (p=0.053)." (PMID 34497771, 2021). "Consistently, cytoplasmic expression of HMGB1 was also detected in breast cancer and human renal clear cell cancer and indicated higher tumor grades." (PMID 34257571, 2021). "We assessed the peripheral blood (PB) neutrophil proportion and the paired serum HMGB1 level of newly diagnosed breast cancer patients and observed that TNBC patient PB had a higher proportion of CD62Ldim neutrophils than that from Non-TNBC patients." (PMID 32943604, 2020). "Basal-like breast cancer with increased HMGB1 expression exhibits pulmonary metastasis earlier, occurring at an average of 23 months." (PMID 32943604, 2020). "Our results suggest that the combination of HMGB1 and CD62Ldim neutrophils is a potential marker for breast cancer lung metastasis and is novel target for future prevention and therapy." (PMID 32943604, 2020). "HMGB1 expression in the primary tumors of patients with breast cancer lung metastasis was higher than that observed in patients without tumor metastasis." (PMID 32943604, 2020). "According to the GEO database, among all of the patients initially diagnosed with breast cancer, patients with high HMGB1 expression are more likely to have breast cancer metastasis, especially in basal-like breast cancer." (PMID 32943604, 2020). "Among them, HMGB1 was found to promote cancer progression and metastasis in different cancers, such as hepatocellular carcinoma, lung cancer, breast cancer, colorectal cancer, prostate cancer, cervical cancer, and ovarian cancer." (PMID 33520999, 2020). "The role of HMGB1 has been reported by research groups worldwide in the genesis of different cancers, such as lung and breast cancer." (PMID 32328193, 2020). "We also found that the expression of HMGB1 was higher in breast cancer tissue compared to normal breast tissue using the tumor database of Oncomine and the Human Protein Atlas." (PMID 31664305, 2019). "In breast cancer cells, cycle, apoptosis, the formation of G4 structures, calreticulin and high mobility group box 1 (HMGB1), as well as T cell activation, were analyzed by flow cytometry and adenosine triphosphate (ATP) by luminescence." (PMID 31731707, 2019). "And HMGB1-induced autophagy was essential for drug resistance of osteosarcoma, leukemia, lung cancer and breast cancer." (PMID 31331356, 2019). "Recently, studies indicated that HMGB1 plays an essential role in chemotherapy sensitivity through modulating protective autophagy in a number of cancers, including breast cancer." (PMID 31664305, 2019). "We not only established a direct interaction between SEPT9 and HMGB1 protein, but also confirmed the interaction between HMGB1 and RB, as it has been reported that intracellular HMGB1 functions as a tumor suppressor in breast cancer by directly binding to RB." (PMID 31426855, 2019). "The high-mobility group box 1 (HMGB1) released from CAFs was demonstrated to stimulate CSCs through the TLR4 receptor in breast cancer." (PMID 31709180, 2019). "In our current study, we found HMGB1 was highly expressed in breast cancer by searching databases of Oncomine and the Human Protein Atlas." (PMID 31664305, 2019). "Studies also have identified that miR-129-5p directly targets HMGB1 in breast cancer and osteosarcoma." (PMID 31664305, 2019). "HMGB1 has been found to promote the proliferation and migration of various types of tumor cells, such as squamous lung cell carcinoma cells, breast cancer cells and hepatocellular carcinoma cells." (PMID 31247032, 2019).
breast carcinoma (continued). "An overexpression of HMGB1 was observed in leukemia, osteosarcoma, breast cancer, lung cancer and prostate cancer and there was also a strong association with their progression or prognosis." (PMID 31331356, 2019). "In breast cancer, miR-129-5p direct regulation of HMGB1 and consequently of autophagy contributes to ameliorate radiosensitivity in vitro." (PMID 31379812, 2019). "It is possible that during breast cancer metastasis, Ac-HMGB1 and LPS each initiate a specific signaling pathway downstream of TLR470." (PMID 31844158, 2019). "Overexpressed HMGB1 in breast cancer was reported to bind to the tumor suppressor Rb and induce cell cycle-arrest and apoptosis." (PMID 29728635, 2018). "In our model, at 18 hours of DHA treatment, it was possible to see an almost complete HMGB1 translocation in MDA-MB-231 breast cancer cells." (PMID 29386662, 2018). "In one study, autophagic CAFs in luminal breast cancer induced stemness in the cancer cells through the secretion of high-mobility group box 1 (HMGB1), resulting in the activation of toll-like receptor 4 in the cancer cells." (PMID 30380628, 2018). "HMGB1 is also upregulated and secreted in other cancer types, including prostate, colon, pancreas and breast cancers, and HMGB1 overexpression, in conjunction with its receptor RAGE, has been associated with a metastatic phenotype and linked to poor prognosis." (PMID 28186988, 2017). "miR-200c inhibits metastasis of breast cancer by downregulating high mobility group protein B1 (HMGB1), which enhances tumor cell motility and suppresses apoptosis." (PMID 27992370, 2017). "Previous studies found that the expression of HMGB1 was much higher in tumor than in the normal tissue counterpart, such as hepatocellular carcinoma, breast carcinomas and colorectal adenocarcinomas." (PMID 28969092, 2017). "Previous studies showed that knockout of the HMGB1 in mouse embryonic fibroblasts or knockdown of HMGB1 in human breast cancer cell lines resulted in a decline in telomerase activity and telomere dysfunction." (PMID 28374746, 2017). "Similar positive predictive values of blood HMGB1 levels have been found in breast cancer, colorectal cancer, liver cancer, and pancreatic cancer." (PMID 28861714, 2017). "A modified but similar kinetic of plasma HMGB1 levels was observed by others in breast cancer patients with locally confined breast cancer receiving neoadjuvant epirubicin/cyclophosphamide followed by docetaxel chemotherapy." (PMID 27457217, 2016). "A TLR4 single-nucleotide polymorphism reduces the interaction between HMGB1 and TLR4 thereby inhibiting antigen presentation which is associated with a poor prognosis of breast cancer patients." (PMID 26948869, 2016). "To yield more information, we selected six well‐defined polymorphisms from the genes encoding HMGB1 and RAGE, and examined their genetic predisposition to breast cancer in a large Han Chinese population from Heilongjiang province." (PMID 27241711, 2016). "Although this factor is an important DAMP that can increase immunogenic responses, HMGB1 increases doxorubicin resistance in neighboring breast cancer cells." (PMID 27933272, 2016). "Several studies report that HMGB1 plays a key role in various types of malignancies, such as breast cancer, gastric cancer and hepatocellular carcinoma." (PMID 26840258, 2016). "The first limitation is the retrospective case–control association design, and such design cannot reveal the possible cause‐effect between HMGB1/RAGE pathway and breast cancer." (PMID 27241711, 2016). "In this study, we show that an epirubicin/docetaxel‐induced increase in the blood levels of HMGB1 during the first days of neoadjuvant chemotherapy of early breast cancer correlates with the long‐term survival of patients." (PMID 27457217, 2016).
breast carcinoma (continued). "In a previous study, we showed that epirubicin/docetaxel combination chemotherapy induces an increase in HMGB1 in the peripheral blood of early breast cancer patients within a few days after administration of chemotherapy." (PMID 27457217, 2016). "The present study confirmed the effect of fibroblast-derived substances in enhancing HMGB1 expression in human breast cancer cells." (PMID 25512109, 2014). "On the other hand, however, Chang and colleagues found that miR-200c inhibits metastasis of breast cancer cells by targeting HMGB1." (PMID 25367080, 2014). "Pre-treatment of breast cancer cells with BCF-CM induced a degree of resistance to Dox in accordance with the increased level of secreted HMGB1." (PMID 25512109, 2014). "BCF-CM significantly induced intracellular HMGB1 protein expression in MDA-MB-231 breast cancer cells as detected by Western blot analysis at all time points tested." (PMID 25512109, 2014). "Overexpression of HMGB1 was discussed in various types of malignancy, containing colorectal carcinoma, breast cancer, hepatocellular carcinoma, pancreatic cancer and prostate carcinoma." (PMID 24837834, 2014). "Intracellular HMGB1 expression was induced in BCF-CM-treated breast cancer cells and also in Dox-treated cells." (PMID 25512109, 2014). "The data reported here indicate the potential of extracellular HMGB1 released from breast cancer cells to exert a paracrine effect on surviving cancer cells enabling them to resist Dox therapy." (PMID 25512109, 2014). "Recent studies report that the expression of HMGB1 is upregulated in several types of malignancies including gastric cancer, breast cancer, nasopharyngeal carcinoma, and squamous cell carcinoma of the head and neck." (PMID 25356587, 2014). "Several chemotherapeutic agents used in the treatment of breast cancer including cyclophosphamide, methotrexate, paclitaxel and doxorubicin induce HMGB1 release into the tumor microenvironment following cell death." (PMID 25512109, 2014). "Increased expression of HMGB1 occurs in many solid tumors, including breast cancer, gastric cancer, colon cancer, and nasopharyngeal carcinoma." (PMID 23866030, 2013). "Recent studies have reported that HMGB1 activity is found in several cancers such as melanoma, colon cancer, breast cancer, and lung cancer." (PMID 23617783, 2013). "An elevated expression of Hmgb1 was observed in certain primary tumors including melanoma and colon, prostate, pancreatic, and breast cancers." (PMID 24453427, 2013). "Further, it has been demonstrated that the TLR4 Asp299 polymorphism affects the binding of HMGB1 to TLR4 and predicts early relapse after chemotherapy in breast cancer patients." (PMID 21854645, 2011). "Furthermore, the XIAOPI formula promotes chemosensitivity to Taxol treatment by inhibiting the CXCL1/HMGB1-mediated autophagy axis, diminishing survival pathways in breast cancer-resistant cells." (PMID 41465435, 2025). "Comparison of the expression of HMGB1 mRNA in patients with breast cancer with luminal A, luminal B, HER2, and basal-like subtypes using microarray and RNA-seq public datasets revealed significantly higher HMGB1 mRNA levels in the basal-like subtype than those in other subtypes." (PMID 40389855, 2025). "TLR2 and HMGB1 correlate with breast cancer progression and poor prognosis." (PMID 40727252, 2025). "Moreover, HMGB1 levels in circulating TRAPs correlates with NETs levels in peripheral blood and with lung metastases in breast cancer patients." (PMID 40391215, 2025). "Similarly, inhibiting Med19 enhances the effectiveness of doxorubicin in breast cancer treatment by downregulating HMGB1 and subsequently suppressing autophagy." (PMID 40723786, 2025). "In breast cancer cells, HMGB1 translocation from the nucleus to the cytoplasm increased the JAK2-STAT3 interaction and induced STAT3 phosphorylation, leading to increased STAT3 target signaling, including the epithelial-mesenchymal transition (EMT) phenotype and PD-L1 expression." (PMID 40389855, 2025).